FLI1 (Fli-1 proto-oncogene, ETS transcription factor)
Diseases named in the same sentence as FLI1 in open-access papers (continued):
Sharing a sentence is not in itself a finding about the gene and the disease.
infection (15 papers, 2008 to 2025). The state of being infected such as from the introduction of a foreign agent such as serum, vaccine, antigenic substance or organism. "This is the first study to examine interactions of FLI1 with candidate Incs or with LRRF1 during infection." (PMID 39404459, 2024). "A recent study demonstrated that Fli-1 represses effector CD8+ T cells responses during anti-infection and antitumor responses." (PMID 36074578, 2022). "A recent role for Fli-1 in regulating the CD8+ T cell response during infection and the antitumor response has also been identified, yet its role in primary CD4+ T cells remains largely elusive." (PMID 36074578, 2022). "Cells were harvested and divided into two parts for Western-blot to determine protein levels and RNA extraction for gene expression profiling 48 hrs after infection with a FLI1-targeting shRNA virus or a LacZ-targeting shRNA virus as a control." (PMID 23894528, 2013). "This low level of Ews-Fli1 expression may have resulted from the Ad-Cre infection; however, the batch of Ad-Cre had been used routinely in the lab to recombine lox sites found on a single chromosome with very high efficiency." (PMID 27191748, 2017). "Venous endothelium appeared as a primary target of infection, as could be confirmed in fli1:GFP transgenic larvae by live imaging and immunohistochemistry." (PMID 21304884, 2011). "To test this hypothesis, we isolated cKit+ cells from mouse fetal liver cells, cultured them for 5 days in presence of mSCF and mTpo upon infection with lentiviruses expressing control shRNA or shRNA directed against Fli-1 or Lmo2 mRNA to repress their expression." (PMID 33733070, 2021). "Infection of adult human fibroblast and mesenchymal cells with an ETV2 virus in combination with FLI1 and ERG1 viruses only modestly induced endothelial genes." (PMID 25780560, 2015). "The fluorescence pattern observed was reminiscent of fli1-promoter-driven expression (endothelium specific), suggesting that DC injection of IAV results in infection of vascular endothelial cells in zebrafish." (PMID 25190709, 2014). "All of the fusion proteins as well as FLI-1 and ERG-1 were readily detected 36 hours following infection." (PMID 18648544, 2008). "The deletion of Fli1 led to increased chromatin accessibility at RUNX motifs, thereby enhancing the biological efficacy of RUNX-driven Teff cells, which demonstrated increased resistance to infection and tumorigenesis." (PMID 39822248, 2024).
hematological malignancies (10 papers, 2017 to 2025). "Aberrant expression of FLI1 is associated with hematological malignancies and solid tumors." (PMID 30867568, 2019). "Along with RUNX1, FLI1 is also a critical regulator of embryonic hematopoiesis; thus, compensatory epigenetic downregulation of RUNX1 and FLI1 may be required for viable embryogenic development in DS, but potentially also results in increased risk of hematological malignancies." (PMID 33547282, 2021). "Aberrant expression of FLI1 may act as a critical driver in the development of hematological malignancies." (PMID 30537986, 2018). "FLI1 is preferentially expressed in hematopoietic cells and tissues, endothelial cells and fibroblasts, and it has been previously reported to act as a major driver of hematological malignancies." (PMID 28410216, 2017). "The CCLE analysis also revealed correlation between the expression of FLI1, WASP, and WIP in hematological malignancies." (PMID 33717090, 2021). "Friend leukemia virus integration 1 (FLI1), an Ets transcription factor family member, has been previously reported to act as a major driver of hematological malignancies." (PMID 28410216, 2017).
vasculopathy (10 papers, 2012 to 2025). "Enhanced expression of endothelial cathepsin B and cathepsin L due to Fli1 deficiency has been shown to be associated with SSc vasculopathy, whereas downregulation of CTSB, CTSL, and CTSV in dermal fibroblasts implicates in SSc dermal fibrosis." (PMID 36768203, 2023). "Cyclophosphamide was demonstrated to exert a beneficial effect on Fli1 deficiency-dependent vasculopathy in a murine SSc model by improving the expression of endothelial Fli1, as well as angiogenesis and vasculogenesis effectors." (PMID 36768203, 2023). "Based on these backgrounds, we investigated the potential role of CCL20/CCR6 in SSc vasculopathy and the contribution of FLI1 deficiency to this process by a series of experiments with clinical samples, cultured endothelial cells, and animal models." (PMID 34774095, 2021). "FLI1 deficiency is a key disease factor regulating a broad spectrum of endothelial behaviors and vascular remodeling associated with SSc vasculopathy, including angiogenesis and vasculogenesis." (PMID 34774095, 2021). "Given that FLI1 bound the CCR6 promoter in HDMECs, CCR6 is a member of molecules involved in the mechanism by which FLI1 deficiency promotes the development of SSc vasculopathy." (PMID 34774095, 2021). "We previously demonstrated that the deficiency of transcription factor Fli1 in endothelial cells is potentially associated with the development of SSc vasculopathy." (PMID 22384200, 2012). "Besides, Fli1 was shown to regulate the activity of a few angiogenesis-related chemokines with pro- or anti-angiogenic properties in the context of SSc-associated vasculopathy." (PMID 36768203, 2023). "Taken together with our recent data regarding the association of the CCL20/CCR6 axis with SSc-PAH, we hypothesized that FLI1 deficiency regulates the CCL20/CCR6 axis in the context of SSc vasculopathy." (PMID 34774095, 2021). "The increased expression of endothelial CCR6 due to FLI1 deficiency may contribute to the development of SSc vasculopathy." (PMID 34774095, 2021). "Although the pathogenesis of SSc vasculopathy still remains unknown, we recently demonstrated that endothelial Fli1 deficiency is potentially associated with the development of vascular changes characteristic for SSc." (PMID 22384200, 2012). "Thus, Fli1 deficiency may serve as a key regulator of skin inflammation, as well as skin fibrosis and vasculopathy, in SSc." (PMID 33964960, 2021). "In conclusion, up-regulation of endothelial CTSB due to Fli1 deficiency may contribute to the development of SSc vasculopathy, especially digital ulcers, while reduced expression of CTSB in lesional dermal fibroblasts is likely to be associated with skin sclerosis in early dcSSc." (PMID 22384200, 2012). "Based on the previous report that implicated lysosomal enzyme cathepsin B as a potential contributor to the development of SSc vasculopathy, we focused on its role in FLI1 and ERG protein degradation." (PMID 32979864, 2021). "CXCL4, a chemokine with anti-angiogenic capacity, may contribute to peripheral SSc vasculopathy by downregulating Fli1 via c-Abl signaling in endothelial cells." (PMID 36768203, 2023). "Since the deficiency of transcription factor Fli1 in endothelial cells is potentially associated with the development of SSc vasculopathy, cutaneous CTSB expression was evaluated by immunostaining in Fli1+/− and wild type mice as well as in SSc and control subjects." (PMID 22384200, 2012). "Endothelial cell-specific Fli1 knockout (Fli1 ECKO) mice reproduce the pathological and morphological features of SSc vasculopathy, such as stenosis of arterioles, dilation capillaries, and increased vascular permeability." (PMID 22384200, 2012).
kidney disease (4 papers, 2010 to 2021). "CXCR3 mediates kidney disease in murine lupus nephritis, and reduction of the transcription factor FLI1 results in amelioration of kidney disease in MRL/lpr mice with concomitant reduction in CXCR3+ T cells and CXCL9/10 expression." (PMID 29568300, 2018). "Overexpression of FLI1 in transgenic mice results in the development of a lupus-like disease, including hypergammaglobulinemia, splenomegaly, B-cell peripheral lymphocytosis, progressive immune complex-mediated renal disease and ultimately premature death from renal failure." (PMID 34763718, 2021). "In contrast, reduced expression of FLI1 in MRL/lpr mice, a murine model of lupus, significantly increases survival and decreases renal disease compared with wild type counterparts." (PMID 34763718, 2021).
benign tumor (1 paper, 2025). "RAH is a rare benign tumor, and the positive staining of markers, including ERG, FLI-1, CD31 and CD34, can contribute to its differential diagnosis." (PMID 40416971, 2025).
hematologic cancers (1 paper, 2019). "Many CIS occurred near genes implicated in hematologic cancers and hematopoietic development (Erg, Ets1, Epo, Il2rb, Flt3, Kras, Stat5b, Fli1)." (PMID 30940846, 2019).
FLI1 also shares sentences with these, for which no sentence is quoted: osteosarcoma (14 papers); neuroblastoma (13); myxoid liposarcoma (11); chronic myeloid leukemia (7); Ewing's sarcoma family tumors (6); liposarcoma (5); hepatocellular carcinoma (4); mesenchymal chondrosarcoma (4); mesenchymal tumors (4); adamantinoma (3); adenocarcinoma (3); cervical carcinoma (3); chondrosarcoma (3); diabetic retinopathy (3); heart defects (3); Hypertension (3); pediatric cancer (3); small cell osteosarcoma (3); undifferentiated sarcoma (3); acute leukemia (2); adenoma (2); bone sarcoma (2); connective tissue tumors (2); endometrial cancer (2); extraskeletal myxoid chondrosarcoma (2); Hodgkins lymphoma (2); leiomyosarcoma (2); liver fibrosis (2); lung adenocarcinoma (2); lymphangioma (2).
A further 94 diseases each share a sentence with FLI1 in 2 papers or fewer.